PDK4 (pyruvate dehydrogenase kinase 4)
Diseases named in the same sentence as PDK4 in open-access papers (continued):
Sharing a sentence is not in itself a finding about the gene and the disease.
Insulin resistance (49 papers, 2007 to 2025). Increased resistance towards insulin, that is, diminished effectiveness of insulin in reducing blood glucose levels. "Conversely, PDK4 deficiency prevented fatty acid-induced mitochondrial dysfunction and insulin resistance via suppression of MAM20,24." (PMID 36973273, 2023). "Pdk4 expression has been shown to be increased in skeletal muscle and heart of obese, insulin resistant, and diabetic animal models, and to be associated with insulin resistance and cardiac dysfunction." (PMID 37626210, 2023). "The results suggest that inhibition of PDK4 (possibly activating SIRT3) can avoid myocardial insulin resistance caused by ANG, and may provide new treatment strategies for diastolic dysfunction and heart disease." (PMID 33739396, 2021). "Obesity was found to be associated with increased PDK4 expression, enhanced MAMs formation, and insulin resistance, which could be ameliorated by PDK4 inhibition." (PMID 33339212, 2020). "Of importance is that deletion of both PDK2 and PDK4 is associated with reduced weight gain, insulin resistance, and adipose tissue inflammation, emphasizing the promising effect of targeting macrophage glucose oxidation in mitigating insulin resistance and tissue inflammation in obesity." (PMID 39198360, 2025). "The question arises of whether Pdk4 overexpression causes insulin resistance or vice versa." (PMID 17949489, 2007). "PDK4, a crucial regulator of the pyruvate dehydrogenase complex, significantly contributes to obesity-related insulin resistance and metabolic dysfunction." (PMID 40652248, 2025). "It has been shown that the expression of PDK4 is significantly upregulated in skeletal muscles of patients with insulin resistance." (PMID 38556697, 2024). "Studies have shown the important regulatory role of PDK4 in the development of insulin resistance in skeletal muscles." (PMID 38556697, 2024). "On the other hand, genetic ablation of Pdk4 protects against obesity-induced hepatic insulin resistance and steatosis." (PMID 36973273, 2023). "Under hunger and some pathological conditions (such as insulin resistance and type 2 diabetes), PDK4 expression is significantly up-regulated." (PMID 36986243, 2023). "Belonging to the PDK superfamily and acting as a glucose sensor, PDK4 has become an attractive target for treatment of various metabolic pathologies including hyperglycemia, insulin resistance and hepatic steatosis." (PMID 37903887, 2023). "PDK4 was included as a well-described marker of muscle insulin resistance and as a potential therapeutic target." (PMID 36790478, 2023). "Lipid accumulation and numerous transcriptional changes in genes associated with insulin resistance and lipid metabolism were noted from day 7, including increased CYP2E1, insulin-like growth factor (IGFβ1), PDK4, and CYP7A1 expressions." (PMID 34631680, 2021). "The involvement of the FOXO1 transcription factor in the etiology of muscle insulin resistance in critical illness is mediated via increased pyruvate dehydrogenase kinase 4 (PDK4) transcription." (PMID 34769017, 2021). "Multiple evidence shows that PDK-4 has an important role in the pathomechanism of metabolic diseases including insulin resistance and hyperglycemia." (PMID 34502172, 2021). "Intriguingly, several studies have shown the positive effect of PDK4 on ER-mitochondria interactions in an obesity-induced insulin resistance model." (PMID 33203874, 2020). "As a mitochondrial enzyme that is abundantly expressed in the heart and skeletal muscle, PDK4 (pyruvate dehydrogenase kinase 4) is significantly upregulated during obesity and insulin resistance." (PMID 33339212, 2020). "Recently, it was suggested that the role of PDK4 in insulin resistance was related to augmented MAMs formation, Ca2+ overload, and mitochondrial dysfunction." (PMID 33339212, 2020). "PDK4 is a mammalian mitochondrial serine kinase protein, which is involved in insulin resistance, a T2DM phenotype." (PMID 28837672, 2017).
Insulin resistance (continued). "The STAT5A-mediated induction of pyruvate dehydrogenase kinase 4 expression by prolactin results in an inhibition of insulin-stimulated glucose transport in fat cells and contributes to insulin resistance." (PMID 29088862, 2017). "The expression of PDK4 is sensitive to insulin, as insulin resistance results in an upregulation of PDK4 expression." (PMID 27649241, 2016). "During insulin resistance, pyruvate dehydrogenase kinase 4 (PDK4) is known to inhibit glucose oxidation by blocking pyruvate to enter into mitochondrial oxidation through phosphorylating the E1 moiety of pyruvate dehydrogenase complex." (PMID 26956801, 2016). "FOXO1 can modulate glucose metabolism in adult cardiomyocytes in insulin resistance and diabetic conditions by inhibiting glucose oxidation preceded by PDK4 activation, subsequently altering the substrate preference for fatty acid and lactate." (PMID 26956801, 2016). "Enhanced expression of FOXO1 downstream target gene PDK4 gene is also observed in high fat and obese animal models of insulin resistance, which adversely regulate insulin actions." (PMID 26956801, 2016). "Insulin tolerance tests did not reveal a significant improvement in either Pdk2 or Pdk4 knockdown mice although Pdk4 knockdown had a trend of improvement of insulin resistance." (PMID 23940800, 2013). "Inactivation of the Pdk4 gene can improve hyperglycemia, glucose tolerance, and insulin resistance in diabetic mice." (PMID 23940800, 2013). "Among these Pdks, Pdk4 is highly inducible by starvation and it is also elevated under insulin resistance." (PMID 23940800, 2013). "Our results indicate that Pdk4 indeed plays a more significant role in the development of hyperglycemia and glucose intolerance in this hepatic insulin resistance model." (PMID 23940800, 2013). "Instead, our data suggest that the role of PDK4 should be contemplated as a possible contributor to high-fat diet- induced insulin resistance." (PMID 22682013, 2012). "It has been suggested that insulin resistance is associated with dysregulation of the PDC in skeletal muscle and that excess insulin would on the other hand down-regulate the expression of PDK4." (PMID 22682013, 2012). "Our data further suggest that the inhibition of pyruvate dehydrogenase by PDK4 is a possible contributor to insulin resistance." (PMID 22682013, 2012). "Instead, the role of PDK4 should be contemplated as a possible contributor to high-fat diet-induced insulin resistance." (PMID 22682013, 2012). "The second model describes the regulation of two nuclear encoded mitochondrial genes that have been associated with insulin resistance, UCP3 and PDK4." (PMID 19787081, 2008). "This overexpression increases the uptake of glucose by muscle tissue and activated the PI3K/Akt-1 pathway by upregulating Akt-1 expression, which in turn leads to a decline in the expression levels of Foxo-1 and Pdk-4 to counteract the excess of glucose and inhibit the insulin resistance." (PMID 37584728, 2023). "In Type 2 diabetic patients with ischemia–reperfusion, elevated PDK4 activity may lead to insulin resistance in the body, and the improvement of myocardial reperfusion may stimulate glucose oxidation." (PMID 33739396, 2021). "al induced acute insulin resistance by constant infusion of Intralipid (a fat emulsion) and lactate for 5 h in rats, resulting in 2 to 3 fold higher PDK4 expression in muscle following insulin infusion, indicating the impaired ability of insulin to suppress PDK4." (PMID 24520982, 2014). "To examine whether Pdk2 or Pdk4 knockout might affect insulin resistance in IrsLDKO mice, we performed insulin tolerance tests." (PMID 23940800, 2013). "From this and other gene knockout studies, it seems likely that a selective inhibition of the Pdk4 activity may be useful to normalize glucose metabolism and improve insulin resistance." (PMID 23940800, 2013). "ER stress potentiates hepatic insulin resistance, and insulin suppresses PDK4 expression." (PMID 23716639, 2013).
Insulin resistance (continued). "However, several studies using high-fat dietary models of insulin resistance indicate that Pdk4 overexpression occurs before the development of insulin resistance." (PMID 17949489, 2007). "In addition, specific expression of Pdk4 could induce insulin resistance, reduction in myocardial glucose oxidation and increase in fatty acid oxidation." (PMID 36726122, 2023). "Although it has not been documented directly that increased Pdk4 mRNA levels can indeed cause insulin resistance, it seems possible that a vicious cycle may exist between these two phenomena." (PMID 17949489, 2007). "Insulin suppresses Pdk4 expression in skeletal muscle and, according to a recent study by Kim and coworkers, this effect is impaired in insulin resistance, suggesting that insulin resistance may indeed induce Pdk4 expression." (PMID 17949489, 2007). "In support of this, previous studies have shown that mice with whole-body deletion of PDK4, a mitochondrial enzyme that inhibits the activity of PDH, are protected against insulin resistance when fed an HFD." (PMID 37865313, 2023). "Pdk4 is upregulated under pathological conditions, such as HFD-induced insulin resistance and T2D32,33." (PMID 35440636, 2022). "Pyruvate dehydrogenase kinase 4 (PDK4) inhibition is a potential avenue for treatment of metabolic disorders such as hyperglycemia and insulin resistance, in addition to cancer and allergies." (PMID 35011562, 2022). "Impaired glucose tolerance is in line with reports of insulin resistance in ALS, and could explain observations of increased expression of pyruvate dehydrogenase kinase 4 (PDK4) in skeletal muscle of ALS patients." (PMID 30936848, 2019). "Our study also provide evidence that lipotoxic muscle are in a state of metabolic inflexibility and link this state to insulin resistance given that insulin treatment failed to reduce PDK4 expression in myotubes cultured under lipotoxic condition." (PMID 24936385, 2014). "Pyruvate dehydrogenase kinase 4 (PDK4) is a member of the PDK/BCKDK protein kinase family, which inhibits the pyruvate dehydrogenase complex by phosphorylation of its subunits, and it also has been previously shown to participate in apoptosis and insulin resistance." (PMID 35178098, 2022). "Although bezafibrate also induced GLUT4 and CPT1b expression in skeletal muscle, IRS and PDK4 expression was not similarly effected; this together with the stable adiponectin gene expression and unrectified dyslipidemia explained why insulin resistance was not improved by bezafibrate." (PMID 24759758, 2014).
Obesity (43 papers, 2008 to 2025). Accumulation of substantial excess body fat. "This study firstly suggests that a negative correlation between the hypo-methylated CpG (cg17075888) on the PDK4 gene and its expression was highly associated with obesity." (PMID 32709145, 2020). "In particular, a CpG (cg17075888 of PDK4), considered as potential therapeutic targets, were associated with complex diseases, including obesity and type 2 diabetes." (PMID 32709145, 2020). "Enhanced expressions of both UCP3 and PDK4 in skeletal muscle have been associated with obesity and type II diabetes in humans." (PMID 19787081, 2008). "Overall, these studies report that adherence to a Mediterranean Diet and/or calorie restriction were associated with decreased DNA methylation in obesity-related genes such as PDK4, KCNQ1, WT1, SH2B1, FTO, BDNF, and PPARGC1A or inflammatory genes such as TNF-α." (PMID 31506096, 2019). "Obesity is associated with an altered methylation and expression of PDK4, while weight loss by gastric bypass surgery is able to normalize the levels of both PDK4 methylation and PDK4 expression to those observed in normal-weight, healthy controls." (PMID 29535681, 2018). "Both PDH and PDK4 protein levels were significantly lower and obesity-independent in malignant tumor tissue compared to benign tumor tissue." (PMID 38247846, 2024). "It was found earlier, that the PDK4 inhibition may alleviate some symptoms of type 2 diabetes in mice; in particular, PDK4 deficiency was found to decrease blood glucose and improved glucose tolerance and insulin sensiti-vity in mice with diet-induced obesity (Jeoung and Harris, 2008)." (PMID 38234967, 2023). "Changes in the activity of the PDK family, including PDK4, mediate the inhibitory effect of fatty acids on glucose metabolism; thus, PDK4 plays a vital role in obesity and metabolic diseases." (PMID 32709145, 2020). "Importantly, we found a significant increase in PDK4 expression in gastric smooth muscle fibers from patients with obesity compared to controls, while ANGPTL4 levels showed a slight but non-significant increase." (PMID 40652248, 2025). "The decrease in PDK-4 expression after Empagliflozin administration was accompanied by a reduction in fatty acid uptake in the liver, suggesting that the protective effect against obesity would actually be the alteration of PDK-4 induced by Empagliflozin." (PMID 40725186, 2025). "Furthermore, a significant positive correlation was observed between ANGPTL4 and PDK4 mRNA levels in patients with obesity, suggesting a link between their expression." (PMID 40652248, 2025). "This process could explain the decrease in PDK1/2 expression and increase in PDK4 expression in the adipose tissue of individuals with severe obesity." (PMID 34552205, 2021). "Furthermore, a recent study demonstrated that obesity-induced increases in PDK4 activity augments MAM stability and suppresses skeletal muscle insulin signaling." (PMID 33195204, 2020). "They showed that some lipid metabolism-related genes (i.e., Mod1, Cyp4a10, Hmgcs2, Acot1, Acot2, Pdk4, Acaa1b, Cpt1, Fabp1, and Acadl) were significantly up-regulated in the intestine of both A/J (obesity-resistant) and C57BL/6J (obesity-prone) mice fed with high fat diet." (PMID 26861690, 2016). "Furthermore, increased acetyl CoA and nicotinamide adenine dinucleotide (NADH) production following high rates of fatty acid oxidation during obesity activates pyruvate dehydrogenase kinase 4 (PDK4), which inhibits PDH, the main enzyme of glucose oxidation, by phosphorylation." (PMID 39109269, 2024). "Furthermore, the increased expression of Pepck and Pdk4 genes (CCGs in the kidneys and liver) with higher levels of blood glucose and serum insulin exacerbated the processes of insulin resistance and diabetes in high-fat-diet-induced obesity." (PMID 29385702, 2018).
Obesity (continued). "This study reveals a novel mechanistic link between obesity and gastric smooth muscle dysfunction, implicating the activation of the PPARD/PDK4/ANGPTL4 pathway." (PMID 40652248, 2025). "Obesity triggers a phenotypic change in gastric SMCs, driven by the activation of the PPARD/PDK4/ANGPTL4 pathway." (PMID 40652248, 2025). "Pyruvate dehydrogenase kinase 4 (PDK4) directly interacts with and stabilizes the IP3R1-GRP75-VDAC1 complex at the MAM interface, and obesity-induced increases in PDK4 activity augment the MAM formation and Ca2+ flux to the mitochondria." (PMID 33195204, 2020). "The correlation of PDK4 and ANGPTL4 expression with markers of mesenchymal immaturity and smooth muscle dedifferentiation underscores their potential as biomarkers and targets for therapeutic intervention in obesity-related gastric dysmotility." (PMID 40652248, 2025). "Notably, PDK4 and ANGPTL4 levels correlate with immaturity and alteration of gastric smooth muscle in patients with obesity." (PMID 40652248, 2025). "Pyruvate dehydrogenase kinase 4 (pdk4) was notable as an exercise‐responsive transcript that demonstrated distinct expression patterns in people with and without obesity." (PMID 36541258, 2022). "The authors reported that the promoter methylation of PGC-1α and PDK4 changed with obesity and was restored to non-obese levels after RYGB-induced weight loss through a global as well as a promoter-specific DNA methylation analysis." (PMID 36295527, 2022). "To study the effect of the HFD-induced obesity in the GCs response, we assessed the dexamethasone-induced expression of FKBP51, PDK4, and KLF15 as readouts to evaluate GC response in the liver, skeletal muscle (gastrocnemius), and white adipose tissue (epididymal fat)." (PMID 33066464, 2020). "Many of the proteins identified in the present study that showed increased expression with obesity are predominantly involved in energy utilization, either fatty acid β oxidation (e.g. malonyl-CoA decarboxylase (MLYCD)) or glucose oxidation (e.g. pyruvate dehydrogenase kinase isozyme 4 (PDK4))." (PMID 30061171, 2018). "First, we identified gene sets related to the function of each obesity-related serum factor: HG/HI (Insr, Irs1, Rps6kb1, Slc2a4, Slc2a5, Slc2a1), TNF-α (Tnfrsf1a, Tradd, Traf2, Fadd), IL-6 (Il6ra, Il6st, Jak1), and fatty acids (PA, LA, Chol; Ffar1, Ffar4, Ppara, Pdk4, Pgc1a)." (PMID 37047207, 2023).